GJB2 (gap junction protein beta 2)
Diseases named in the same sentence as GJB2 in open-access papers (continued):
Sharing a sentence is not in itself a finding about the gene and the disease.
deafness (continued). "By controlling the concentration of SB supplementation in combination with CX26+ vesicle purification, large-scale production of highly purified iCX26GJCs suitable for high-throughput drug screening or regenerative therapy for GJB2-related deafness may be possible." (PMID 33968919, 2021). "However, the lack of any functional variants in GJB2, GJB3, GJB6 and TRMU suggested that nuclear genes may not play active roles in deafness expression." (PMID 32400865, 2020). "Although many studies indicated that, similar to Western countries, mutations in GJB2, SLC26A4, and mtDNA 12S rRNA (MIM #561000) are the major cause of the genetic deafness in China, the molecular etiology of non‐syndromic deafness in the Chinese population has not been systematically investigated." (PMID 30693673, 2019).
KID syndrome (62 papers, 2011 to 2026). Keratitis (and hystrix-like) ichthyosis deafness (KID/HID) syndrome is a rare congenital ectodermal disorder characterized by vascularizing keratitis, hyperkeratotic skin lesions and hearing loss. "We report the case of a 35-year-old male patient with a genetically confirmed diagnosis of keratitis–ichthyosis–deafness (KID) syndrome caused by a heterozygous GJB2 mutation (p.D50N)." (PMID 41517259, 2025). "Heterozygous variants in the GJB2 gene also cause a condition known as “Keratitis-ichthyosis-deafness syndrome” (OMIM #148210), an inherited ectodermal disorder." (PMID 39595064, 2024). "KID syndrome, due to heterozygous mutations in the Gap junction beta-2 (GJB2) gene that encodes connexin-26 (Cx26), is complicated by chronic skin infections in approximately half of reported cases, with CMC being the most common." (PMID 36986378, 2023). "Two unrelated patients from Cameroon with KID syndrome were reported to have heterozygous GJB2-p.D50N mutation." (PMID 34609590, 2022). "Keratitis ichthyosis deafness (KID) syndrome is caused by point mutations in the GJB2 gene encoding Connexin 26 (Cx26) which result in aberrant activation of connexin hemichannels." (PMID 34916582, 2021). "Mutations in GJB2 are associated with several skin disorders including keratitis-ichthyosis-deafness (KID) syndrome a severe skin disorder that also presents with sensorineural hearing loss." (PMID 33807656, 2021). "Both hereditary and sporadic cases of KID syndrome have been reported; the hereditary form is linked to dominant mutations in GJB2." (PMID 33807656, 2021). "In the GJB2‐deficient mice model for Keratitis‐ichthyosis‐deafness (KID) syndrome, an altered calcium distribution in epidermis results in abnormal lipid processing, thus implying GJB2 as an essential factor in barrier homoeostasis." (PMID 30372788, 2019). "The present study characterizes the effects of three KID syndrome-causative Gjb2 mutations (Cx26-G12R, -G45E and -D50N) on hemichannel activities, cell death and immune responses of the cells with information on the Ca2+ concentrations for each experiment." (PMID 30150638, 2018). "Various experiments have shown that KID syndrome-causative GJB2 mutations result in the formation of Cx26 hemichannels with aberrant activity." (PMID 30150638, 2018). "In conclusion, we clearly demonstrated that aberrant hemichannels form due to the KID syndrome-causative Gjb2 mutations Cx26-G12R, -G45E and -D50N." (PMID 30150638, 2018). "In the present study, we examined how three Gjb2 mutants (Cx26-G12R, -G45E and -D50N) causative of KID syndrome affected the formation and function of the hemichannels and gap junctions in transfected HeLa cells." (PMID 30150638, 2018). "Summarizing the results of hemichannel activities in the present study, we clearly demonstrated the formation of aberrant hemichannels by the KID syndrome-causative Gjb2 mutations Cx26-G12R, -G45E and -D50N." (PMID 30150638, 2018). "The diseases-phenotype has been demonstrated in a mouse model expressing the GJB2 c.50C > T, p.Ser17Phe mutation, a mutation reported to cause KID syndrome in humans." (PMID 28158657, 2017). "This is the first report of an Argentinean patient with KID syndrome due to the p.Asp50Asn mutation in the GJB2 gene." (PMID 27141831, 2016). "KID syndrome is caused by heterozygous missense mutations in GJB2, the gene encoding connexin 26 (Cx26)." (PMID 27141831, 2016). "In this work, we identified a clinical case of KID syndrome with mutation p.Asp50Asn in GJB2, associated to sensorineural hearing loss and several skin alterations." (PMID 27141831, 2016). "Several mutations in the GJB2 gene causing KID syndrome are known: p.Gly11Arg, p.Gly12Arg, p.Asn14Tyr, p.Ser17Phe, p.Ala40Val, p.Asp50Asn, and p.Gly54Glu localized in the N-terminus or in the first extracellular domain." (PMID 25575739, 2015).
KID syndrome (continued). "The results of DNA analysis in the three patients confirmed the clinical diagnosis of KID syndrome in patient 1 [heterozygous mutation p.Asp50Asn (c.148G>A) in GJB2] and Clouston syndrome in patients 2 and 3 [mutation p.Gly11Arg (c.31G>C) in GJB6]." (PMID 25575739, 2015). "KID syndrome is mainly caused by a heterozygous germ line missense mutation in GJB2 (Entrez Gene ID: 2706) encoding connexin 26 (Cx26) (RefSeq: NM_004004.5)." (PMID 24785414, 2014). "We encountered a girl with KID syndrome from obviously healthy parents, and sequence analysis of GJB2 revealed a heterozygous missense mutation, p.Gly45Glu, in the patient." (PMID 24785414, 2014). "We describe this form of KID syndrome caused by the reversion of the GJB2 nonsense mutation p.Tyr136X that would otherwise have confined the effect of another dominant lethal mutation, p.Gly45Glu, in the same allele." (PMID 24785414, 2014). "We describe a lethal form of keratitis-ichthyosis-deafness (KID) syndrome caused by the reversion of the GJB2 nonsense mutation p.Tyr136X that would otherwise have confined the effect of another dominant lethal mutation, p.Gly45Glu, in the same allele." (PMID 24785414, 2014). "It is also known that, besides KID syndrome, biallelic loss of function of GJB2 causes autosomal recessive non-syndromic hearing loss (NSHL)." (PMID 24785414, 2014). "Mutations in cases of KID syndrome have been rarely reported in patients of African descent, but p.Asp50Asn mutation in the GJB2 gene have been previously only reported in a black patient from the Emirates." (PMID 23924173, 2013). "In this article, we report on two unrelated Cameroonian patients with KID syndrome presenting with heterozygous p.Asp50Asn mutation in the GJB2 gene." (PMID 23924173, 2013). "The cause of KID syndrome was identified as a germline missense mutation in the GJB2 (gap junctionβ-2) gene encoding for connexin-26, which is essential for gap function formation in various tissues." (PMID 24151560, 2013). "Although no human conditions have been described that closely resemble CKCSID, keratitis-ichthyosis-deafness (KID) syndrome shares more than one similar clinical sign, and is caused by mutations in the GJB2 gene encoding connexin-26." (PMID 22253609, 2012). "Disease-associated mutations in GJB2 whose positions coincide with p.A40V of GJB2 have also been detected in the keratitis ichthyosis deafness (KID) syndrome." (PMID 21731760, 2011). "However, most cases of KID syndrome arise from autosomal dominant, often de novo, mutations in the GJB2 gene-particularly the D50N variant." (PMID 41305774, 2025). "KID syndrome arises from missense mutations in the GJB2 gene." (PMID 38827992, 2024). "The p.Asp50Asn is the most frequent pathogenic GJB2 variant associated with KID syndrome." (PMID 37892203, 2023). "KID syndrome could be caused by heterozygous dominant missense mutations in GJB2 (gap junction protein beta 2) and GJB6 (gap junction protein beta 6) genes, encoding connexin 26 (Cx26) and Cx30, respectively." (PMID 32054030, 2020). "GJB2 mutations causative of KID syndrome have been shown to induce elevated hemichannel activities." (PMID 30150638, 2018). "In light of these findings and emerging evidence linking GJB2 mutations to neurological and skeletal anomalies, this report aims to contribute a hypothesis-generating perspective on the multisystemic manifestations of KID syndrome." (PMID 41305774, 2025). "The GJB2 gene is expressed in a variety of tissues, including several ectodermal epithelia affected in KID syndrome: the corneal epithelium, epidermis of skin, cochlea, and hair follicles." (PMID 41517259, 2025). "More recently, some researchers have proposed that PEODDN represents a mosaic form of keratitis-ichthyosis-deafness (KID) syndrome, caused by a mutation in GJB2 (gap junction protein beta 2), which encodes the gap junction protein Cx26 (connexin-26)." (PMID 40861600, 2025).
KID syndrome (continued). "The skin and eye malformations found in the affected calf resemble human keratitis-ichthyosis-deafness syndrome (OMIM 148,210), a rare disorder caused by dominant acting variants in GJB2 that encodes for connexin 26, a gap junction protein." (PMID 34996433, 2022). "Prominent gene-annotation clusters in both Group I and Group II cells encode proteins involved in nervous system development, including the neurotrophic factors Grp, Bdnf and Nrtn and the keratitis-ichthyosis-deafness syndrome gene Gjb2." (PMID 30355452, 2018). "Syndromic deafness caused by GJB2 gene mutation is often accompanied by skin diseases, including keratitis–ichthyosis–deafness (KID) syndrome, Bart–Pumphrey syndrome (BPS), hystrix-like ichthyosis with deafness (HID) syndrome, and Vohwinkel syndrome." (PMID 35457072, 2022). "Two rare congenital disorders, keratitis–ichthyosis–deafness (KID) syndrome [OMIM 148210] and Clouston syndrome (hidrotic ectodermal dysplasia 2) [OMIM 129500], are caused by mutations in genes coding connexin proteins (GJB2 and GJB6, respectively), and both of them have skin manifestation." (PMID 25575739, 2015). "Interestingly, in the group of Japanese patients with bilateral sensorineural hearing loss, it is not uncommon to find GJB2 p.Gly45Glu carriers, but none of them are affected by KID syndrome." (PMID 24785414, 2014).
breast carcinoma (45 papers, 2010 to 2024). "For instance, higher GJB2 or GJA1 protein amounts are associated with a less favorable outcome in breast cancer." (PMID 38956497, 2024). "GJB2 was associated with early-stage breast cancer development through the regulation of cancer stemness." (PMID 37689745, 2023). "Increased expression of GJB2 was associated with poor prognosis in various tumors, including breast cancer, pancreatic cancer, lung adenocarcinoma, and esophageal squamous cell carcinoma." (PMID 35936685, 2022). "In that over 1% of the general population worldwide are estimated to be carriers of mutant alleles of GJB2 it remains critical to determine if this population as a whole, or in part, are at an increased risk of developing breast cancer." (PMID 26439696, 2015). "It has been reported that GJB2 expression was negatively associated with progression status in breast cancer tissues and may function as a regulator of breast tumorigenesis." (PMID 37561809, 2023). "Therefore, we recommend a large epidemiologic study of breast cancer frequency in patients with loss-of-function GJB2 mutations compared to familial healthy controls." (PMID 26439696, 2015). "However, although our results suggest an increased breast cancer risk to patients with loss of function GJB2 mutations, it is important to note that our mouse model does not recapitulate all Cx26 mutants." (PMID 26439696, 2015). "It is unknown if patients with loss-of-function GJB2 mutations have a greater susceptibility to breast tumorigenesis or aggressive breast cancer progression." (PMID 26439696, 2015). "Together, our results suggest that loss of Cx26 predisposes the mammary gland to chemically induced mammary tumour formation which may have important implications to patients with GJB2 mutations." (PMID 26439696, 2015). "GJB2 and SCN9A have been linked to invasion and proliferation in prostate, lung, gastric, and breast cancer, as well as metastasis and worse prognosis in several cancer types." (PMID 38177502, 2024). "Many studies have explored the role of GJB2 in tumors, including breast cancer, liver cancer, and colorectal cancer." (PMID 35936685, 2022). "GJB2 regulates cell migration and colonization and thus aggressive phenotype in breast cancer." (PMID 35326596, 2022). "GJB2 expression is elevated in many tumor cell lines, tumor tissues, and breast cancer." (PMID 36016609, 2022). "In addition, GJB2 knockdown increases the probability of carcinogenesis in breast cancer." (PMID 36639804, 2023). "Moreover, the knockdown of GJB2 in human breast cancer cell lines using shRNA resulted in a significant decrease in the proliferative ability and an increase in the migratory ability of breast cancer cells." (PMID 37561809, 2023). "Up-regulated expression of COL10A1, MMP11, CST1, GJB2, MMP1, MMP13, and CEACAM6; down-regulated expression of ADH1B, CIDEC, THRSP, GPD1, TIMP4, FABP4, and SCARA5 genes was common in breast cancers of the two populations." (PMID 31292488, 2019). "The expression of GJA1/Cx43, GJA3/Cx46 and GJB2/Cx26 and, for the first time, GJA6/Cx30 and GJB1/Cx32 was revealed both in normal human mammary glands and breast carcinomas." (PMID 25383624, 2014). "We disclosed the expression of five connexin isotypes by confirming the production of GJA1/Cx43, GJA3/Cx46 and GJB2/Cx26 and detecting, for the first time, GJA6/Cx30 and GJB1/Cx32 both in the human pre-menopausal mammary gland and breast carcinomas." (PMID 25383624, 2014). "Based on mRNA expression data, a comprehensive screening for five connexin isotypes, GJA1/Cx43, GJA3/Cx46, GJB2/Cx26, GJA6/Cx30 and GJB1/Cx32 was performed at the protein level in normal pre-menopausal breast glands and in a cohort of cancers representing all grades and major breast cancer subtypes." (PMID 25383624, 2014).
sensorineural hearing loss (43 papers, 2006 to 2025). "Autosomal recessive sensorineural hearing loss associated with the STRC gene is the second most common cause of hereditary sensorineural hearing loss after GJB2 mutations, accounting for approximately 2–8% of cases depending on the population studied." (PMID 41562875, 2025). "This perspective offers a novel therapeutic strategy for addressing GJB2-associated hereditary sensorineural hearing loss." (PMID 40365300, 2025). "GJB2 mutations, which encode the gap-junction protein connexin 26, represent the most common genetic cause of congenital and early-onset non-syndromic sensorineural hearing loss worldwide." (PMID 41463124, 2025). "Congenital sensorineural hearing loss is a significant global health issue, primarily driven by genetic factors, such as mutations in the GJB2 gene." (PMID 39151510, 2024). "This study aimed to verify the frequency of three GJB2 mutations in non-syndromic sensorineural deafness in the Iraqi population." (PMID 35126756, 2021). "Our data concluded that the GJB2 c.35delG and c.235delC gene mutations were the main cause of autosomal recessive non-syndromic sensorineural hearing loss in the Iraqi deaf population." (PMID 35126756, 2021). "In summary, sensorineural hearing loss linked to GJB2 gene mutations is one of the most common inherited conditions found worldwide affecting as many as 1/2000 live births." (PMID 32300592, 2020). "c.205T > C (p.Phe69Leu) was identified as a novel dominant pathogenic variant of GJB2 associated with prelingual nonsyndromic sensorineural hearing loss.GJB2 mutation is the most common cause of genetic deafness." (PMID 32090102, 2020). "We identified the novel GJB2 mutation c.524C > A (p.P175H), which segregated with high frequency and was involved in progressive sensorineural hearing loss." (PMID 28102197, 2017). "The molecular etiology of nonsyndromic sensorineural hearing loss (SNHL) in subjects with only one detectable autosomal recessive GJB2 mutation is unclear." (PMID 27057829, 2016). "There are reports of patients with sensorineural hearing loss caused by co-existing mutations in GJB2 or SLC26A4 and the mitochondrial gene, and one enlarged vestibular aqueduct syndrome patient with compound mutations in both SLC26A4 and GJB2 respectively." (PMID 26061099, 2015). "Hereditary deafness affects about 1 in 2,000 children, and mutations in the gap junction protein, beta 2, 26 kDa gene (GJB2), also known as connexin 26 (CX26), are the most common genetic causes of congenital bilateral non-syndromic sensorineural hearing loss." (PMID 24387126, 2014). "It has been over 15 years since the GJB2 gene encoding the Cx26 gap junction (GJ) protein was identified as a susceptibility gene for sensorineural deafness." (PMID 25386120, 2014). "Mutation of the GJB2 gene, which encodes the connexin 26 (Cx26) gap junction (GJ) protein, is the most common cause of hereditary, sensorineural hearing loss." (PMID 25386120, 2014). "The gap junction beta-2 (GJB2) gene, which encodes connexin 26 (a component of gap junctions), is the most common cause of sensorineural hearing loss (SNHL)." (PMID 23151025, 2012). "Studies on a mutation associated with Vohwinkel syndrome (p.D66H) and the GJB2 p.R75W missense mutation, associated with sensorineural deafness and PPK, both located in EC1, have both a dominant negative effect on Cx26 gap junction assembly." (PMID 22547955, 2011). "In LER (CD−M2), Ush1c, Otogl, Gjb2, and Eps8 were associated with NSHL; Ush1c and Clrn1 with Usher syndrome, Six1 with branchiootorenal syndrome; Gjb2 with skin phenotype and HL; Gata3 with hypoparathyroidism, sensorineural hearing loss, and renal dysplasia; and Col9a2 with Stickler syndrome." (PMID 39684410, 2024). "Mutations in the GJB2 gene disrupt the formation or functioning of Cx26, leading to impaired communication between cells in the auditory system and resulting in progressive, sensorineural hearing loss." (PMID 38069203, 2023).